ERVK3-1 (endogenous retrovirus group K3 member 1)
Synonyms: HERV-K(HML6-1)
Gene: Protein-coding gene on chromosome 19 (58,305,347 to 58,316,812, forward strand). Ensembl gene ENSG00000142396.
Diseases named in the same sentence as ERVK3-1 in open-access papers:
ERVK3-1 is named in the same sentence as 3 diseases in open-access papers, as found by Europe PMC text mining. Sharing a sentence is not in itself a finding about the gene and the disease. The quoted sentences say what the papers report.
glioma (2 papers, 2022 to 2025). A benign or malignant brain and spinal cord tumor that arises from glial cells (astrocytes, oligodendrocytes, ependymal cells). "HERVs, particularly HML-6 and its gene product ERVK3-1, have been linked to glioma progression, since HERV expression correlates with DNA hypomethylation at specific loci." (PMID 40565099, 2025). "Further analysis of ERVK3-1 is necessary to elucidate its role in glioma oncogenesis and recurrence." (PMID 35477752, 2022).
tumor (2 papers, 2022 to 2024). "Our results have demonstrated several implications for the role of HML-6 and ERVK3-1 in the tumor biology of GBM as well as the potential clinical applications of future studies." (PMID 35477752, 2022). "Further analysis of the role of HML-6 and ERVK3-1 with respect to tumor biology may present avenues for assessing ERVK3-1 as a drug target." (PMID 35477752, 2022). "In addition, obtaining data from paired primary and recurrent GBM samples would grant further insight into the role of HML-6/ERVK3-1 in tumor recurrence." (PMID 35477752, 2022). "Thus, future studies investigating the relationship between ERVK3-1 expression and the tumor immunophenotype would provide critical insight in this regard." (PMID 35477752, 2022). "While our work has formed the basis for ERVK3-1 to be considered a potential prognostic marker for GBM survival, development of a curated database with tumor samples sequenced for HERV and ERVK3-1 expression would be highly beneficial for future clinical application of our findings." (PMID 35477752, 2022).
ERVK3-1 also shares sentences with these, for which no sentence is quoted: lung adenocarcinoma (2 papers).